KLF11 (KLF transcription factor 11)
Diseases named in the same sentence as KLF11 in open-access papers (continued):
Sharing a sentence is not in itself a finding about the gene and the disease.
dyslipidemia (3 papers, 2012 to 2024). "Dyslipidemia and hypertension were most common in HNF1B‐MODY (52.9% dyslipidemia, 58.3% hypertension) and KLF11‐MODY (75% dyslipidemia, 100% hypertension), while were less common in ABCC8‐MODY (18.2% dyslipidemia, 25.0% hypertension)." (PMID 39511990, 2024).
gastric cancer (3 papers, 2021 to 2023). A primary or metastatic malignant neoplasm involving the stomach. "Mechanistically, KMT2A activated β-catenin signaling, which served as a coactivator of KLF11, and promoted the expression of specific gastric cancer stemness-related molecules." (PMID 38025523, 2023). "To address the issue on the molecular mechanism of KMT2A regulating β-catenin activation-induced stemness in gastric cancer, we identified the β-catenin-binding nuclear protein KLF11 by performing a Co-IP/MS analysis gastric cancer cells." (PMID 38025523, 2023). "It has been described for example that KLF11 promotes invasion and migration in gastric cancer through activation of Twist124." (PMID 34997020, 2022). "We demonstrated that miR-10b-5p targets PTEN of gastric cancer cells and KLF11 of fibroblasts and mediates the communication of gastric cancer cells and fibroblasts via TGFβ1/TGFβR1 signaling." (PMID 33754012, 2021). "Moreover, it was identified by a dual luciferase reporter assay that KLF11 binds directly with the promoters of specific gastric cancer stemness-related molecules, including SOX2 and FOXM1." (PMID 38025523, 2023). "The result showed a binding of β-catenin with KLF11 in gastric cancer cells." (PMID 38025523, 2023). "Mechanistically, KMT2A activated the translocation of β-catenin into the nucleus of gastric cancer cells, and then, β-catenin served as a coactivator of KLF11, which promoted the expression of specific gastric cancer stemness-related molecules, including SOX2 and FOXM1." (PMID 38025523, 2023). "Hence, to clarify whether β-catenin can bind with KLF11 in gastric cancer cells, we carried out a Co-IP assay followed by western blotting detection." (PMID 38025523, 2023).
Glucose intolerance (3 papers, 2014 to 2025). Glucose intolerance (GI) can be defined as dysglycemia that comprises both prediabetes and diabetes. "Glucose tolerance tests (GTTs) showed that a modest induction of KLF11 in db/db mouse livers markedly improved glucose intolerance after an intraperitoneal glucose injection compared with control Ad-GFP-injected db/db mice." (PMID 24586865, 2014). "The authors proposed that this variant may demonstrate incomplete penetrance for glucose intolerance, supporting the view that routine inclusion of KLF11 in MODY genetic testing may not be warranted." (PMID 41153735, 2025).
aortic aneurysm (2 papers, 2021 to 2024). A ruptured aneurysm located in the wall of the proximal portion of the descending aorta proceeding from the arch of the aorta. "By elucidating the specific pathays through which KLF11 exerts its protective effects on aortic aneurysm and diabetic atherosclerosis, we gain valuable insights into potential therapeutic strategies for managing vascular diseases in both diabetic and non-diabetic populations." (PMID 39462409, 2024). "Overall, we established endothelial KLF11 as a potentially novel factor protecting against AAA and a potential target for intervention in aortic aneurysms." (PMID 33507881, 2021).
hepatocellular carcinoma (2 papers, 2018 to 2020). A malignant tumor that arises from hepatocytes. "In hepatocellular carcinoma, KLF11 had a significant influence on proliferation and apoptosis." (PMID 32331236, 2020).
ischemic stroke (2 papers, 2021 to 2022). A stroke disorder caused by obstruction of blood flow to the brain, due to thrombotic (local blood clot formation) or embolic (due to a blood clot or other material traveling from another site) event. "We previously found that genetic deletion of KLF11 in mice increased brain infarction, while endothelium-selected transgenic overexpression of KLF11 reduced the cerebral infarct volume after ischemic stroke." (PMID 36403074, 2022). "We have previously demonstrated that KLF11 was significantly downregulated in ischemic stroke and genetic deletion of KLF11 aggravated ischemic brain damage and worsened neurobehavioral performance in mice." (PMID 36403074, 2022). "We have also recently shown that endothelium-targeted transgenic overexpression of KLF11 in mice improved sensorimotor deficits at the acute phase of ischemic stroke." (PMID 36403074, 2022). "We have previously reported that genetic deletion of KLF11 in mice delayed the recovery of sensorimotor function at 7 d of ischemic stroke." (PMID 36403074, 2022). "In contrast, endothelium-targeted transgenic overexpression of KLF11 preserved BBB structural and functional integrity, and therefore, conferred brain protection in ischemic stroke." (PMID 36403074, 2022). "We have previously demonstrated that endothelium-targeted transgenic overexpression of KLF11 promotes expression of the endothelial tight junction protein, ZO-1 and decreased BBB leakage and brain neuroinflammation in experimental ischemic stroke." (PMID 36403074, 2022).
myelodysplastic syndrome (2 papers, 2012 to 2016). A clonal hematopoietic disorder characterized by dysplasia and ineffective hematopoiesis in one or more of the hematopoietic cell lines. "Recently, KLF11 was also shown to be aberrantly hypermethylated in myelodysplastic syndromes." (PMID 22428009, 2012).
renal fibrosis (2 papers, 2022 to 2024). A final common manifestation of a wide variety of chronic kidney diseases characterized by glomerulosclerosis and tubulointerstitial fibrosis. "In summary, we have defined a critical role for KLF11 in regulation of both inflammation and fibrosis in unilateral ureteric obstruction, a well characterized model of renal fibrosis." (PMID 35413089, 2022). "KLF11 inhibits genes associated with TGF-β pathways and fibrosis during cardiac and renal fibrosis." (PMID 39462409, 2024). "Other KLF family members have been linked to podocyte dysfunction and renal fibrosis but the role of KLF11 in mediating renal inflammation and fibrosis has not been established." (PMID 35413089, 2022). "We sought to test the hypothesis that KLF11 regulates inflammation and fibrosis in unilateral ureteral obstruction, a well-established model of renal fibrosis." (PMID 35413089, 2022). "We sought to test the hypothesis that KLF11 deficiency promotes CKD through upregulation of pro-inflammatory and pro-fibrogenic signaling pathways in murine unilateral ureteral obstruction (UUO), a well-established model of renal fibrosis." (PMID 35413089, 2022).
sarcoma (2 papers, 2023 to 2025). A usually aggressive malignant neoplasm of the soft tissue or bone. "Additionally, KLF11 has been identified as a negative regulator in sarcoma CSCs, where its epigenetic silencing leads to prolonged YAP activation and poor prognosis." (PMID 40316546, 2025). "Low KLF11 expression was associated with poor prognosis and poor chemotherapy response in sarcoma patients, and as a TGF-β signaling pathway mediator, KLF11 could be a druggable suppressor for sarcoma cancer stem cells." (PMID 37107646, 2023).
Ureteral obstruction (2 papers, 2022 to 2023). Obstruction of the flow of urine through the ureter. "KLF11 is a Krüppel-type zinc finger protein whose deficiency enhances chemokine generation and fibrosis in murine unilateral ureteral obstruction and highly induced by TGF-β." (PMID 36875100, 2023). "Based on the strong and diffuse staining of tubular epithelial cells in WT mice subjected to UUO, we hypothesize that KLF11 deficiency may exacerbate tubular injury in response to ureteric obstruction." (PMID 35413089, 2022).
uterine fibroids (2 papers, 2012 to 2013). "First, we studied the KLF11 promoter via sequencing of bisulfite-treated genomic DNA from uterine leiomyoma and myometrial tissues from 8 subjects." (PMID 22428009, 2012). "We previously demonstrated the downregulation of KLF11 expression in uterine leiomyoma tissues compared with normal matched myometrial tissue." (PMID 22428009, 2012). "In uterine leiomyoma, the majority of the 16 CpG dinucleotides in the KLF11 promoter were consistently methylated." (PMID 22428009, 2012). "Six of the eight uterine leiomyoma samples showed increased DNA methylation of the KLF11 promoter." (PMID 22428009, 2012). "Although the mechanism involved in KLF11-regulated cell proliferation is not fully understood, we demonstrated for the first time that KLF11 is epigenetically regulated by DNA methylation, with hypermethylation correlating with a repressed state in uterine leiomyoma." (PMID 22428009, 2012). "To validate that DNA methylation leads to gene silencing of the tumor suppressor genes KLF11, DLEC1, and KRT19, we assessed mRNA levels in vivo using real-time RT-PCR in uterine leiomyoma and matched myometrial tissues." (PMID 22428009, 2012).
alcohol dependence (1 paper, 2020). Physical and psychological dependence on alcohol. "For example, protein levels of Kruppel‐like factor 11 (KLF11) have been shown to increase in the postmortem PFC of subjects with alcohol dependence." (PMID 31840818, 2020).
aneurysm (1 paper, 2021). Bulging or ballooning in an area of an artery secondary to arterial wall weakening. "Here we found that endothelial KLF11 expression was reduced in the ECs from human aneurysms and was time dependently decreased in the aneurysmal endothelium from both elastase- and Pcsk9/AngII-induced AAA mouse models." (PMID 33507881, 2021).
Brain atrophy (1 paper, 2022). Partial or complete wasting (loss) of brain tissue that was once present. "In this study, we are the first to demonstrate that genetic deletion of KLF11 further worsened TBI-induced brain atrophy and neuronal death in the cerebral cortex and hippocampal CA1 regions in mice after TBI." (PMID 36403074, 2022). "In comparison with WT controls, KLF11 KO mice exhibited a larger volume of brain atrophy and larger areas of atrophy in cross-sectional areas, suggesting an increased gross tissue loss after TBI." (PMID 36403074, 2022).
brain trauma (1 paper, 2022). "However, the underlying mechanisms by which KLF11 genetic deficiency activates cerebral astrocytes remain to be further investigated in brain trauma." (PMID 36403074, 2022). "Our data highlight the essential role of KLF11 in maintaining white matter integrity in response to brain trauma." (PMID 36403074, 2022). "Up to now, the role and molecular mechanisms of KLF11 in regulating the pathogenesis of brain trauma is poorly understood." (PMID 36403074, 2022). "Elucidating the functional importance of KLF11 in brain trauma may lead us to discover novel pharmacological targets for the development of effective therapies against TBI." (PMID 36403074, 2022). "Elucidating the functional importance of KLF11 in TBI may lead us to discover novel pharmacological targets for the development of effective therapies against brain trauma." (PMID 36403074, 2022). "Our data indicate that KLF11 plays a protective role in the pathogenesis of brain trauma." (PMID 36403074, 2022). "Collectively, these data suggest that KLF11 genetic deficiency in mice enhanced cerebral inflammatory burdens in post-trauma brains, and KLF11 regulation of cerebral inflammation may represent one of the major mechanisms for its protective role in brain trauma." (PMID 36403074, 2022). "However, the molecular events and regulatory roles of KLF11 in brain trauma remain unclear." (PMID 36403074, 2022). "In this study, we demonstrated that genetic deletion of KLF11 aggravated long-term sensorimotor deficits and learning/memory impairments following TBI, suggesting a critical role of KLF11 in the regulation of both sensorimotor and cognitive functions after brain trauma." (PMID 36403074, 2022).
carotid atherosclerosis (1 paper, 2025). A thickening and loss of elasticity of the walls of carotid arteries that occur with formation of atherosclerotic plaques. "Correlation analysis revealed that the KLF11 levels in the aorta were positively correlated with the ABCA1 and ABCG1 levels in normal controls and carotid atherosclerosis patients, suggesting that KLF11 regulates ABCA1 and ABCG1 expression." (PMID 40397286, 2025). "Moreover, KLF11 levels in the aorta were positively correlated with the ABCA1 and ABCG1 levels in normal controls and carotid atherosclerosis patients." (PMID 40397286, 2025).
chronic kidney disease (1 paper, 2022). Impairment of the renal function secondary to chronic kidney damage persisting for three or more months. "Interventions to increase KLF11 expression may provide a potential therapeutic target to decrease renal inflammation and fibrosis in chronic kidney disease." (PMID 35413089, 2022).
Cognitive impairment (1 paper, 2022). Abnormal cognition is characterized by deficits in thinking, reasoning, or remembering. "Of importance, myelin loss and axonal damage had a strong positive correlation with sensorimotor and cognitive deficits in KLF11 KO mice following TBI." (PMID 36403074, 2022). "We further examined whether KLF11 genetic deletion affects TBI-induced cognitive impairment in mice." (PMID 36403074, 2022). "Reduced neuronal densities in peri-lesional CTX and CA1 regions may contribute to worsened sensorimotor deficit and cognitive impairment in KLF11 KO mice after TBI compared with WT controls." (PMID 36403074, 2022).
fatty liver (1 paper, 2023). "Hepatic expression of KLF11 was reduced in both these models, while overexpression of KLF11 in HFD-fed mice and in db/db mice prevented the development of fatty liver via induction of PPARα-mediated expression of fatty acid oxidation genes, such as Cpt1a, Mcad, Cyp4a10, and Cyp4a14." (PMID 36902112, 2023).
gastroparesis (1 paper, 2021). Paralysis of the muscles of the stomach wall resulting in delayed emptying of the gastric contents into the small intestine. "MiR-10b-5p regulates development and function of ICCs and pancreatic β cells through the KLF11-KIT pathway, in murine models, knockout of mir-10b in KIT+ cells led to DM and gastroparesis." (PMID 33806716, 2021).
glioblastoma (1 paper, 2023). The most malignant astrocytic tumor (WHO grade IV). "To investigate whether these genes with H4K5acK8ac-preferred promoters regulate glioblastoma stem-like properties, i. e., marker gene expression for stem cells and sphere formation efficiency, we disrupted ZNF883, RFX4, KLF11, and ZNF835 by siRNA knockdown in 0316-GSC cells." (PMID 37759202, 2023).
glioma (1 paper, 2023). A benign or malignant brain and spinal cord tumor that arises from glial cells (astrocytes, oligodendrocytes, ependymal cells). "It was thus concluded that KLF11 promotes the progression of glioma through positive regulation of HJURP, and that both proteins could be used as biomarkers for glioma diagnosis and prognosis." (PMID 37025176, 2023).
Impaired glucose tolerance (1 paper, 2014). An abnormal resistance to glucose, i.e., a reduction in the ability to maintain glucose levels in the blood stream within normal limits following oral or intravenous administration of glucose. "Conversely, loss of KLF11 function in db/m mice modestly increased blood glucose levels and impaired glucose tolerance, but not insulin tolerance." (PMID 24586865, 2014).
ischemia (1 paper, 2022). A hypoperfusion of the BLOOD through an organ or tissue caused by a PATHOLOGIC CONSTRICTION or obstruction of its BLOOD VESSELS, or an absence of BLOOD CIRCULATION. "In another study, we also reported that KLF11 serves as a co-regulator of PPARγ to protect mice against ischemia-induced cerebrovascular injury." (PMID 36403074, 2022).
lung adenocarcinoma (1 paper, 2023). A carcinoma that arises from the lung and is characterized by the presence of malignant glandular epithelial cells. "Here, we report that KLF11 inhibits lung adenocarcinoma (LUAD) cell proliferation and promotes chemotherapy sensitivity by participating in the GPX4-related ferroptosis pathway." (PMID 37248295, 2023). "Intriguingly, reversion to GPX4 expression significantly attenuated the toxic response of KLF11-promoted chemotherapy to lung adenocarcinoma cells." (PMID 37248295, 2023). "KLF11 inhibits lung adenocarcinoma cell proliferation and promotes chemotherapy sensitivity by repressing transcription of GPX4 and promoting ferroptosis." (PMID 37248295, 2023).
memory impairment (1 paper, 2022). "Genetic deletion of KLF11 further exacerbated memory impairment in mice after TBI when compared with WT controls, as evidenced by showing less exploration time in the target quadrant." (PMID 36403074, 2022).
neuroblastoma (1 paper, 2024). Neuroblastoma (NB) is the most common solid, extracranial childhood tumor. "A positive correlation between KLF11 and MAO‐B after ethanol exposure was found in both human neuroblastoma SH‐SY5Y cells and rat brains." (PMID 38429921, 2024).
osteosarcoma (1 paper, 2023). A usually aggressive malignant bone-forming mesenchymal neoplasm, predominantly affecting adolescents and young adults. "Genome-wide CRISPR screen led to the identification of a druggable suppressor of sarcoma cancer stem cells, the Krueppel-like factor 11 (KLF11), which if pharmacological activated in synergy with chemotherapy could be improve the success rate for osteosarcoma treatment." (PMID 37120540, 2023).
panic disorder (1 paper, 2020). An anxiety disorder characterized by multiple unexpected panic attacks with persistent concern of recurring attacks. "Given these close links between KLF11 and MAOA function, the KLF11 (TIEG2) gene on chromosome 2p25.1 might constitute a prime, yet uninvestigated candidate gene in the panic disorder/MDD spectrum." (PMID 32524199, 2020).
parasite infections (1 paper, 2025). "Our previous genome linkage analyses on asymptomatic parasite infections in these populations suggested the locus containing KLF11 (LOD score ≈ 2.5), consistent with the result observed here." (PMID 40627625, 2025).
Peritoneal Fibrosis (1 paper, 2013). Disorder characterized by a wide range of structural changes in PERITONEUM, resulting from fibrogenic or inflammatory processes. "The peritoneal fibrosis score (12.3 ± 1.8) in these animals calculated using the murine adhesion scoring system was also similar to that in wildtype animals, although significantly different from that obtained in Klf11-/- animals." (PMID 23555910, 2013).
Renal atrophy (1 paper, 2022). Atrophy of the kidney. "In particular, KLF11 deficiency is associated with increased renal atrophy, interstitial fibrosis, and interstitial inflammation." (PMID 35413089, 2022). "We found that renal atrophy was more severe in KLF11 KO mice subjected to UUO, comparted to WT mice with UUO." (PMID 35413089, 2022).
thrombosis (1 paper, 2022). "In a ferric chloride induced thrombosis model, occlusion time was significantly reduced in KLF11 KO mice." (PMID 35413089, 2022).
trauma (1 paper, 2022). "Genetic deletion of KLF11 worsened brain trauma-induced sensorimotor and cognitive deficits, brain tissue loss and neuronal death, and white matter injury in mice." (PMID 36403074, 2022).
type 1 diabetes (1 paper, 2025). "Type 1 diabetes was diagnosed in the patient with a de novo c.40_41dupGC (p.Val15Glnfs*41) mutation in KLF11." (PMID 41153735, 2025). "A patient with a de novo c.40_41dupGC (p.Val15Glnfs*41) variant in the KLF11 gene was clinically diagnosed with type 1 diabetes." (PMID 41153735, 2025).